ATRN (attractin)
Description:
Involved in the initial immune cell clustering during inflammatory response and may regulate chemotactic activity of chemokines. May play a role in melanocortin signaling pathways that regulate energy homeostasis and hair color. Low-affinity receptor for agouti (By similarity). Has a critical role in normal myelination in the central nervous system (By similarity).
Synonyms: MGCA; DPPT-L
Tractability: Antibody: UniProt places it where antibodies can reach, with high confidence; its Gene Ontology location is reachable by antibodies, with high confidence; UniProt predicts a signal peptide or a membrane-spanning region. PROTAC: ubiquitination databases record sites on it; its protein half-life has been measured.
Gene: Protein-coding gene on chromosome 20 (3,471,018 to 3,651,118, forward strand). Ensembl gene ENSG00000088812.
Subcellular location: Cell membrane (Isoform 1); Secreted (Isoform 2); Secreted (Isoform 3)
Subcellular location (Human Protein Atlas): Cytosol; Predicted to be secreted
Gene Ontology:
Molecular function: signaling receptor activity
Cellular component: extracellular exosome; extracellular region; plasma membrane
Genetic constraint (gnomAD): Loss-of-function variants: 47 observed, 151.58 expected, observed/expected ratio (o/e) 0.31, 90% interval 0.24 to 0.4. The upper end of that interval is the gene's LOEUF score, 0.4, which puts it in group 1 of 6, group 1 being the genes least tolerant of losing a copy. Missense variants: 1,298 observed, 1,624.6 expected, observed/expected ratio (o/e) 0.8, 90% interval 0.76 to 0.84. Synonymous variants: 596 observed, 592.52 expected, observed/expected ratio (o/e) 1.01, 90% interval 0.94 to 1.08.
Homologues: Orthologues: chimpanzee ATRN (99% identical), macaque ATRN (99% identical), rabbit ATRN (95% identical), dog ATRN (95% identical), pig ATRN (94% identical), guinea pig ATRN (94% identical), mouse Atrn (93% identical), rat Atrn (93% identical), tropical clawed frog atrn (74% identical), zebrafish atrn (70% identical). Paralogues in human: ATRNL1 (58% identical), MEGF8 (27% identical), LAMA5 (16% identical), LAMA2 (15% identical), LAMA3 (15% identical), LAMA1 (15% identical), LAMB4 (14% identical), LAMB1 (14% identical), LAMB2 (14% identical), LAMC1 (13% identical), LAMC3 (12% identical), HSPG2 (12% identical), and 15 more.
Diseases named in the same sentence as ATRN in open-access papers:
ATRN is named in the same sentence as 28 diseases in open-access papers, as found by Europe PMC text mining. Sharing a sentence is not in itself a finding about the gene and the disease. The quoted sentences say what the papers report.
Obesity (6 papers, 2013 to 2026). Accumulation of substantial excess body fat. "Attractin, the membrane-bound isoform, with sequence similarity to the mouse mahogany protein, forms a receptor controlling obesity." (PMID 34869343, 2021). "ATRN is a co-receptor for Agouti regulation of pigmentation and obesity in MC1R and MC4R signaling pathways." (PMID 34869343, 2021). "Attractin (ATRN) is a neuropeptide involved in melanocortin signaling and regulation of food intake, which suppresses diet-induced obesity." (PMID 23947536, 2013).
schizophrenia (3 papers, 2019 to 2023). A major psychotic disorder characterized by abnormalities in the perception or expression of reality. "Schizophrenia patients with ATRN mutations have more proportion in abnormal testosterone level, illustrating the relationship between ATRN and testosterone level." (PMID 34869343, 2021). "To establish the contribution made by ATRN expression level to testosterone levels and dimorphic effects, we then purposefully selected 14 patients with ATRN mutations who had been diagnosed with schizophrenia, including five men and nine women." (PMID 34869343, 2021). "In addition, there is a strong correlation between abnormal testosterone levels in schizophrenia patients with ATRN mutations." (PMID 34869343, 2021). "Previous researches have been reported that chromosome position where ATRN is located is highly related to schizophrenia." (PMID 34869343, 2021). "This locus harbors four strong candidate genes for schizophrenia: attractin (ATRN), pantothenate kinase 2 (PANK2), oxytocin (OXT), and arginine–vasopressin (AVP)." (PMID 34869343, 2021). "Besides, He found that cDNA FLJ58441 is highly similar to attractin, and it has a high expression level in schizophrenia patients." (PMID 34869343, 2021). "Of the total of 34 proteins screened, 5 proteins associated with psychoneuroimmune pathways in schizophrenia were analyzed, which could be potential new analytes: drebrin, GMF-β, BDNF, RAB3GAP1, and attractin." (PMID 31849731, 2019). "It should also be admitted that among proteins significantly differed in quantitative measure, GPX3, IGKC, C2, and ATRN (adjusted p < 0.01) did not pass the significance level in the validation cohort of subjects with schizophrenia due to large deviation." (PMID 36747015, 2023).
glioma (2 papers, 2017 to 2023). A benign or malignant brain and spinal cord tumor that arises from glial cells (astrocytes, oligodendrocytes, ependymal cells). "GO analysis on the list of the DEPs identified by mass spectrometry using the PANTHER Classification System showed that 3 cell adhesion molecules, NRP1, NRP2 and ATRN, were putative GDNF receptors in glioma cells with roles in biological adhesion and growth." (PMID 29088765, 2017).
sporadic amyotrophic lateral sclerosis (2 papers, 2021 to 2023). Sporadic amyotrophic lateral sclerosis is a amyotrophic lateral sclerosis in which there is no known cause, such as no family history. "In humans, ATRN is a candidate gene for sporadic amyotrophic lateral sclerosis, ATRN plasma levels are altered in early-onset Alzheimer’s disease (AD) patients prior to symptoms, and its gene expression is reduced in Parkinson disease (PD) patients." (PMID 34235405, 2021). "ATRN has been identified as a potential gene for sporadic amyotrophic lateral sclerosis in humans." (PMID 38201267, 2023).
abdominal aortic aneurysm (1 paper, 2022). Enlargement and ballooning of the vessel that supplies arterial blood to the abdomen, pelvis and legs. "In addition, the level of attractin in the blood was proposed to be used to predict the slow or rapid growth of abdominal aortic aneurysms in humans, because the level of attractin in the blood significantly correlates with the future growth of abdominal aortic aneurysms." (PMID 36361589, 2022).
benign prostatic hyperplasia (1 paper, 2023). A non-cancerous nodular enlargement of the prostate gland. "ATRN is a predictive biomarker in prostate cancer because it distinguishes prostate cancer from benign prostatic hyperplasia." (PMID 37519786, 2023).
cervical cancer (1 paper, 2023). A primary or metastatic malignant neoplasm involving the cervix. "The present study revealed that the N-glycopeptide of MASP1, LUM, ATRN, CO8A, CO8B and CO6 may be potential biomarkers for predicting the efficacy of chemotherapy for cervical cancer." (PMID 37519786, 2023).
COVID-19 (1 paper, 2024). A disease caused by infection with severe acute respiratory syndrome coronavirus 2. "For instance, plasma levels of serumamyloid A protein, C-reactive protein, Alpha-1-acid glycoprotein 1,mannose-binding protein C, haptoglobin, and attractin were significantly elevatedin the COVID-19-related AVB group." (PMID 39076308, 2024).
melanism (1 paper, 2015). "Loss-of-function mutations in two additional and related pigment type-switching components, Attractin and Mahogunin, cause melanism in the laboratory mouse or rat, but these mutations also cause brain abnormalities and would probably be subject to negative selection in natural populations." (PMID 25695801, 2015). "(Additional, less frequent causes of melanism in some mammals include mutations of beta-defensin 103 [an alternative ligand for MC1R], Attractin [an accessory receptor for ASIP], or Mahogunin [an E3 ubiquitin ligase that acts upstream of the MC1R])." (PMID 25695801, 2015).
mental disorder (1 paper, 2021). A disease that has its basis in the disruption of mental process. "Though multiple functions have been discovered, little is known about the role of attractin and the molecular mechanisms in mental disorders." (PMID 34869343, 2021). "The information of patients suffering from mental disorder in the hospital was collected to analyze the relationship between the expression level of ATRN and testosterone level." (PMID 34869343, 2021).
neuroblastoma (1 paper, 2025). Neuroblastoma (NB) is the most common solid, extracranial childhood tumor. "Fluorescently labeled ATRN and MGRN1 colocalize in HEK293T cells and interactions have been observed by co-immunoprecipitation (co-IP) experiments conducted in Neuro2A neuroblastoma cells." (PMID 41178558, 2025).
prion disease (1 paper, 2013). A transmissible disease that is caused by a protein that is able to induce abnormal folding of normal cellular proteins, leading to characteristic spongiform brain changes, which are associated with neuronal loss without an inflammatory response. "Mice lacking the E3 ubiquitin ligase, mahogunin ring finger-1 (MGRN1) or the type I transmembrane protein, attractin (ATRN) develop age-dependent CNS vacuolation that is histologically similar to that associated with prion diseases, without the accumulation of protease-resistant PrPSc." (PMID 23383230, 2013).
psoriasis (1 paper, 2021). An autoimmune condition characterized by red, well-delineated plaques with silvery scales that are usually on the extensor surfaces and scalp. "ATRN mRNA expression in lesional skin of psoriasis patients was 19.5-fold lower (p < 0.001) and in psoriasis non-lesional skin it was 12.4-fold lower (p < 0.001) compared with healthy control skin." (PMID 34884858, 2021). "ATRN mRNA expression level was 1.6-fold higher in non-lesional skin of psoriasis patients when compared with lesional skin of psoriasis patients (p < 0.05)." (PMID 34884858, 2021). "In psoriasis uninvolved skin, positive correlations were found between the expression levels of CREB1 and LEF1 (r = 0.66, p < 0.05), USF1 and PNOC (r = 0.81, p < 0.05), MITF and ATRN (r = 0.58, p < 0.05), MITF and NURR1 (r = 0.56, p < 0.05) and MITF and MAPK14 (r = 0.75, p < 0.01)." (PMID 34884858, 2021).
tumor (5 papers, 2010 to 2024). "There were 253 genes (13.6%) that had decreased expression shared across tumor types, including NPTXR, SCG2, B4GAT1, and ATRN." (PMID 36909536, 2023). "The mRNA expression level of six soluble factors already recognized in cancer biology (POSTN, TNC, CSPG2, LOXL1, ATRN, FBS1) increases in response to IGF-I stimulation, suggesting that these factors play some role in stimulating tumour cell proliferation and metastasis." (PMID 20051100, 2010).
cancer (2 papers, 2010 to 2020). A tumor composed of atypical neoplastic, often pleomorphic cells that invade other tissues. "Conversely, 28 of cancer-related genes were downregulated by shNrf1, of which 6 genes (i.e., HIF1A, STAT5B, IGF1R, TGFBR1, ATRN, and FZD6) were upregulated by Nrf1α−/− to varying extents." (PMID 32273945, 2020).
brain disease (1 paper, 2024). "Among them, 8 differential urinary proteins were previously reported to be closely associated with brain disease, including NP, FZD1, B2M, EPCR, ATRN, MB, CA1and VPS4A." (PMID 38836960, 2024).
disorders of the central nervous system (1 paper, 2021). "To address a possible role of ATRN in disorders of the central nervous system, we created an atrn knockout zebrafish line and performed behavioral tests." (PMID 34869343, 2021).
infection (1 paper, 2024). The state of being infected such as from the introduction of a foreign agent such as serum, vaccine, antigenic substance or organism. "Interestingly, we detected increased levels of attractin (ATRN) in patients with early infection." (PMID 38672194, 2024).
neurological disorders (1 paper, 2023). "According to these reports, it is highly probable that the ATRN/MEGF8-MGRN1 pathway is involved in the development of various neurological disorders." (PMID 38201267, 2023).
ATRN also shares sentences with these, for which no sentence is quoted: Alzheimer disease (1 paper); diabetes (1); fungal infections (1); liver disease (1); memory impairment (1); Parkinson disease (1); postherpetic neuralgia (1); prostate carcinoma (1); Salmonella Infections (1).